ENSG00000286905 (novel protein)
Gene: Protein-coding gene on chromosome 2 (3,532,008 to 3,558,333, reverse strand). Ensembl gene ENSG00000286905.
Genetic constraint (gnomAD): Missense variants: 278 observed, 283.09 expected, observed/expected ratio (o/e) 0.98, 90% interval 0.89 to 1.09. Synonymous variants: 138 observed, 107.85 expected, observed/expected ratio (o/e) 1.28, 90% interval 1.11 to 1.47.